OXT (oxytocin/neurophysin I prepropeptide)
Diseases named in the same sentence as OXT in open-access papers (continued):
Sharing a sentence is not in itself a finding about the gene and the disease.
Obesity (continued). "Our data demonstrate that adolescents and young adults with severe obesity had a significant reduction in serum OXT levels 12 months following SG compared to those receiving standard therapy, primarily mediated by reductions in BMI." (PMID 37373292, 2023). "Our study sheds light on the effects of SG on serum OXT levels in adolescents and young adults with obesity, a sparse area of research." (PMID 37373292, 2023). "Lastly, the OXT pathways that are possibly involved in obesity entail the inhibition of the activity of the food-related pathway, and the reward-related food motivation along with the decrease in food intake by controlling compensatory hedonic eating." (PMID 36358953, 2022). "Having presented the recent information on the human studies regarding the involvement of OXT in obesity/diabetes, we will present the basic research studies on this scientific issue." (PMID 36358953, 2022). "It is beyond the scope of this review to present all the human studies using OXT as a therapeutic intervention in obesity." (PMID 36358953, 2022). "Diabetes, a metabolic disorder with major degenerative complications will be discussed in this manuscript in conjunction with obesity since OXT functions share therapeutic effects in both diseases." (PMID 36358953, 2022). "In particular, hypothalamic OXT has an anorectic action; therefore, modulating this pathway is anticipated to reduce obesity and high blood glucose levels." (PMID 36064966, 2022). "Our study adds to this discussion by showing that male individuals with obesity also differ in the OXT system on grounds of a comorbid ED, pointing toward a complex interplay of OXT signaling, body weight regulation and eating behavior." (PMID 36042529, 2022). "Yet, there is a scarcity of studies looking at OXT function in relation to undercontrolled eating patterns and across the overweight spectrum, including patients with obesity and BED." (PMID 36042529, 2022). "Recently, the oxytocin (OXT) signaling pathway has emerged as an attractive target for treating obesity." (PMID 34646154, 2021). "Central administration of OXT reduces diet-induced obesity, and antagonism of central OXT receptors is obesogenic." (PMID 31912136, 2020). "The major finding of this study is that in an animal model of obesity with hyperglycemia (the db/db mouse) chronic OXT treatment led to a reduction in visceral adipose tissue inflammation." (PMID 32819381, 2020). "In rodent models of obesity, chronic central or peripheral infusions of OXT have been shown to decrease weight gain and improve insulin resistance." (PMID 32819381, 2020). "The neuropeptide hormone oxytocin (OXT) is emerging as an important part of the gut-brain axis and as a promising treatment of obesity, T2D, and addiction." (PMID 29596446, 2018). "In conclusion, we identify MYT1Lmutations as a cause of syndromic obesity, and establish MYT1L as a member of the leptin-melanocortin-SIM1 pathway, with downstream loss of OXT associated with MYT1L mutations a potential therapeutic target." (PMID 28859103, 2017). "Postnatal chemical ablation of Sim1 expressing neurons leads to hyperphagic obesity and reduced expression of OXT and TRH." (PMID 25954163, 2015). "OXT is a naturally existing peptide in mammals and has shown central anti-obesity and anti-diabetic effects per our rodent studies." (PMID 23700406, 2013). "Using mouse models, our previous studies revealed that central administration of OXT can work to treat or prevent against dietary obesity." (PMID 23700406, 2013). "Taken together, for the first time, we provided clinical evidence demonstrating that OXT nasal spray works to treat obesity in human patients." (PMID 23700406, 2013). "The therapeutic advantages of OXT and its analogs in treating obesity and diabetes can be further increased given that OXT has social-neuropsychiatric benefits which can possibly aid to control metabolic disease." (PMID 23700406, 2013).
Obesity (continued). "Based on findings in our studies, next step pharmaceutical and clinical studies are warranted to design OXT analogs that have optimal therapeutic effects via peripheral administration to treat obesity, diabetes and related metabolic diseases." (PMID 23700406, 2013). "Here, following our recent work showing the effect of peripheral OXT delivery in treating obesity in mice, the current work demonstrated that OXT nasal spray can effectively treat human obesity and the related lipid disorders." (PMID 23700406, 2013). "Our research further demonstrated that OXT can work in the brain to improve the neural regulation of metabolism and thereby counteract obesity and obesity-related metabolic abnormalities in mouse models." (PMID 23700406, 2013). "The literature surrounding measurement of plasma OXT concentrations in Prader–Willi syndrome is conflicting, with some authors finding it is decreased relative to the degree of obesity, while others have reported that both plasma and cerebrospinal fluid OXT is increased." (PMID 38019584, 2024). "While OXT expression may have decreased due to the development of obesity, the trend of decreased cell density in the AAV-Cre group led us to hypothesize that the AAV-Cre virus may impact PVN neuronal survival." (PMID 38227343, 2024). "Given OXT’s anorexigenic effects and bone anabolic properties, we sought to understand the effects of SG (the most commonly used MBS to induce weight loss in adolescents with moderate to severe obesity) on OXT levels in youth." (PMID 37373292, 2023). "The potential role of OXT as a therapy for obesity has been recently investigated." (PMID 37780616, 2023). "We examine, for the first time, associations of OXT with body composition and bone endpoints in 25 youth 13–25 years old with severe obesity who underwent sleeve gastrectomy (SG) and 27 non-surgical controls (NS)." (PMID 37373292, 2023). "Studies have highlighted the anorexigenic properties of OXT and its role in modulating caloric intake and energy homeostasis, with recent trials investigating the use of intranasal OXT as a potential therapeutic intervention in the management of obesity." (PMID 37373292, 2023). "Differential regulation of DNA methylation of the OXTR gene might contribute to this OXT-sensitive state in obesity, and this might be of particular relevance for the subgroup of individuals with BED showing impulsive eating behavior." (PMID 36042529, 2022). "When comparing circulating OXT concentrations between individuals with obesity and normal weight, higher, unchanged or decreased concentrations have been reported for obesity." (PMID 36042529, 2022). "In addition to the concerns about sex-specific results from OXT treatment, careful selection of the conditions in which oxytocin treatment should be beneficial for obesity and its comorbidities, and their relevance for human pathology needs to be determined." (PMID 36358953, 2022). "Selective OXT analogs are a promising therapeutic avenue for obesity as they could provide a longer duration of action to increase efficacy and selectivity to the OXT receptor to avoid unwanted off-target effects." (PMID 36232550, 2022). "In addition, there is evidence that OXT is involved in reversing insulin resistance and glucose intolerance, thus reducing obesity." (PMID 35959009, 2022). "Although the precise mechanism that increases OXT and AVP expression by CRTC deficiency remains unknown, the increase in OXT and AVP expression may be a homeostatic adaptation to HFD or obesity." (PMID 35020776, 2022). "Interestingly, a recent study showed that a single dose of intranasal OXT improves performance on an inhibitory control task in males with overweight and obesity." (PMID 36042529, 2022). "Oxytocin (OXT) has emerged as an attractive target for treating obesity." (PMID 36232550, 2022).
Obesity (continued). "Studies in OXT KO mice have indicated that the genetic absence of OXT is associated with enhanced initial and sustained intake of sucrose solutions, and a strong link between OXT deficiency, late-onset obesity and decreased sympathetic tone." (PMID 36358953, 2022). "In addition, because OXT KO mice and OXTR KO mice show significantly increased body weight, the OXT/OXTR system appears to be strongly involved in obesity and/or control of food intake." (PMID 32719656, 2020). "Interestingly, the circulating levels of OXT are reduced in obesity, and intranasal treatment with OXT led to a metabolic shift from using carbohydrates to fat." (PMID 32423100, 2020). "Since obesity has been described as a state of chronic inflammation, dysfunction of the OXT/OXTR system may exacerbate inflammatory diseases/disorders related to obesity such as hypertension, diabetes, and heart disease." (PMID 32819381, 2020). "OXT has gained attention as a putative treatment for obesity and type 2 diabetes (T2D)." (PMID 32819381, 2020). "Our previous study using mouse models had shown that enhancing the intra-brain action of OXT can prevent against the development of obesity and obesity-related diabetic symptoms such as insulin resistance, glucose intolerance, pancreatic islet hypertrophy and steatosis against dietary overnutrition." (PMID 23700406, 2013). "Interestingly, our recent research demonstrated that the intra-brain action of OXT can lead to reversal of obesity as well as related glucose and insulin disorders in mouse models." (PMID 23700406, 2013). "In this study we further asked whether the potential effect of OXT in treating diabetes is completely dependent on obesity control by OXT." (PMID 23700406, 2013). "Subsequently, similar anti-obesity effects of OXT were reported to occur in rat models." (PMID 23700406, 2013). "Herein, grounded in our recent findings, we continued to investigate whether OXT has effects to treat obesity and related metabolic abnormalities in humans, and further explored in rodent models whether OXT and its analogs have anti-diabetic effects that could be dissociable from obesity control." (PMID 23700406, 2013). "Thus, the collection of our data in this work, together with our recent findings, demonstrated that the benefits of OXT in treating metabolic diseases are multi-faceted, range from obesity control to body weight-independent improvements of insulin sensitivity and insulin secretion." (PMID 23700406, 2013). "While five of these exercised a direct and unique effect on obesity only, both pathologies were jointly affected by the remaining three, namely cortisol, NPY, and OXT." (PMID 35959009, 2022). "NPY, cortisol, and OXT played a key role in directly propagated stress response to PTSD and obesity as well as in cascades recruiting other metabolic mediators." (PMID 35959009, 2022). "We present data using a long-acting OXT analog with improved potency to reduce food intake and body weight in DIO animals which improves on the limitations of OXT as an anti-obesity drug intervention." (PMID 34646154, 2021). "Indeed, only increased levels of OXT expressed in response to stress were predicted to jointly reduce severity of symptoms in both PTSD and obesity." (PMID 35959009, 2022). "Obesity is known to increase expression of RAGE, and it is possible that in our DIO Sprague Dawley rats increased transport which needs to be investigated for ASK2131 vs. OXT in a future study." (PMID 36232550, 2022). "Differential DNA gene methylation might play a role in OXT signaling along this cognitive control pathway, especially in the highly impulsive phenotype which is represented by BED on the obesity spectrum." (PMID 36042529, 2022). "Mice lacking OXT in the PVH are more sensitive to HFD-induced obesity due to reduced energy expenditure, and pharmacogenetic activation of OXT neurons in the PVH increases energy expenditure in mice." (PMID 35020776, 2022).
Obesity (continued). "Interestingly, with the exception of the thyroid hormone T3, all cascades involving OXT were predicted to concurrently alleviate the effects of stress on PTSD severity and obesity." (PMID 35959009, 2022). "Moreover, oxytocin (OXT), Neuropeptide-Y (NPY), and cortisol supported an almost direct propagation of stress to PTSD and obesity with different net effects." (PMID 35959009, 2022). "For example, mice lacking OXT or its receptor exhibit mild or late-onset obesity, although normal body weight has also been reported." (PMID 31912136, 2020). "Experiments in TSE PhenoMaster metabolic cages confirmed increased food intake and decreased locomotor activity but no change in energy expenditure (using body mass as a covariate), indicating that hyperphagia is the major driver of obesity in mice lacking Trpc5 in OXT neurons." (PMID 38959890, 2024). "Therefore, the aim of our study was to fill this research gap by investigating potential epigenetic differences in the OXTR in individuals on the obesity spectrum with BED (BED +) versus without BED (BED −) in order to further elucidate the role of OXT in impulsive eating behavior." (PMID 36042529, 2022). "In model organisms, peripheral administration of OXT reduces food intake, enhances energy expenditure, and prevents or attenuates weight gain in rodent models of diet-induced obesity in rodent models of genetic forms of obesity, as well as in non-human primates with diet-induced obesity." (PMID 34646154, 2021). "In the present study, we investigated potential epigenetic differences in the OXTR gene in a sample of individuals with obesity with and without a comorbid BED in order to further elucidate the potential contribution of the OXT system to disordered eating behavior and body weight regulation." (PMID 36042529, 2022). "Herein, to study if OXT treatment has a beneficial effect on beta cells, we used streptozotocin (STZ)-induced diabetic mouse model which suffers from beta cell damage and insulin secretion impairment which resemble T1D and late-stage T2D, but does not have overeating or obesity." (PMID 23700406, 2013).
schizophrenia (40 papers, 2012 to 2024). A major psychotic disorder characterized by abnormalities in the perception or expression of reality. "The OXT gene has been implicated in several disorders, including autism spectrum disorder, social anxiety disorder, and schizophrenia." (PMID 39221148, 2024). "Clozapine targeting ITIH3 and OXT is a second-generation antipsychotic medication classified as atypical, which is utilized in the management of treatment-resistant schizophrenia and to reduce the risk of suicide in individuals with schizophrenia." (PMID 39221148, 2024). "Recent studies have found that genetic polymorphisms in the OXTR and OXT genes in humans have been significantly related to schizophrenia and that OXTR and OXT gene variants have been involved in schizophrenia vulnerability and warrant independent replication." (PMID 37153633, 2023). "Sex-associated differences in both schizophrenia and the OXT peripheral system suggest the involvement of gonadal steroid hormones." (PMID 36979271, 2023). "Improvement in schizophrenia psychopathology, associated with higher plasma OXT levels, is observed during the midluteal phase, when estrogens levels are high." (PMID 36979271, 2023). "Previous studies have identified oxytocinergic dysfunction in people with schizophrenia, and single-nucleotide polymorphisms in the OXT gene contribute to schizophrenia vulnerability." (PMID 37445607, 2023). "On a genetic basis, the involvement of single-nucleotide polymorphisms of the oxytocin gene (OXT) in schizophrenia vulnerability has been proven." (PMID 35806096, 2022). "A small number of studies report associations of plasma OXT levels with social cognitive capacity in schizophrenia patients, the avoidance of angry faces or the perception of faces as happier." (PMID 30481342, 2019). "Recently, higher OXT serum levels in patients with schizophrenia have been found to be associated with reduced symptom severity compared to patients with lower OXT serum levels." (PMID 22510359, 2012). "The impact of OXTR polymorphisms on prosocial attitudes in schizophrenia extends reports of an influence of peripheral OXT levels on prosocial symptom scores, emotion recognition, social cognition and trust in schizophrenia." (PMID 23284802, 2012). "Given that E2 stimulates OXT synthesis and release, prolactin-sparing antipsychotics that act protectively against estrogens deficiency may act against OXT dysregulation in schizophrenia as well." (PMID 36979271, 2023). "In addition, recent studies support a positive association between plasma OXT and functionality in schizophrenia, whereas lower endogenous OXT levels have been linked to acute positive symptomatology." (PMID 36979271, 2023). "Consequently, OXT is considered a regulator of human behavior, which indicates that the oxytocinergic system may be implicated in schizophrenia symptomatology." (PMID 36979271, 2023). "Additionally, peripheral concentrations of OXT modulate resting brain activity differently in male and female patients with schizophrenia (e.g., low OXT levels are associated with lower amplitude of low-frequency fluctuations in the frontal cortex in females, but in posterior cingulate in males)." (PMID 36979271, 2023). "Moreover, introducing verbal IQ, AVLT and age as control variables to the analysis revealed another association in schizophrenia patients: Basal OXT levels were significantly and inversely associated with MET-CE for positive emotional valences (r = -0.468, p<0.01)." (PMID 32255800, 2020). "For instance, patients with schizophrenia exhibited lower levels of OXT after trust-related interactions compared to healthy controls, namely when participants were asked to share an important secret with the experimenter, an action requiring trustworthiness." (PMID 36979271, 2023). "Studies indicate that the endogenous OXT system is perturbed in individuals diagnosed with schizophrenia compared to healthy individuals." (PMID 36979271, 2023).